SLCO1B3 (solute carrier organic anion transporter family member 1B3)
Diseases named in the same sentence as SLCO1B3 in open-access papers (continued):
Sharing a sentence is not in itself a finding about the gene and the disease.
colorectal cancer (15 papers, 2017 to 2026). A primary or metastatic malignant neoplasm that affects the colon or rectum. "Therefore, we cloned several DNA fragments of the promoter regions of the Lt-SLCO1B3 and Ct-SLCO1B3 variants and analyzed their luciferase activity using hepatocellular and colorectal cancer cell lines." (PMID 36986600, 2023). "SLCO1B3 can promote the proliferation and metastasis of colorectal cancer by activating the STAT3 pathway." (PMID 38710698, 2024). "Ct-SLCO1B3 mRNA has been detected in several cancerous tissues including breast, prostate, and colorectal cancer." (PMID 36986600, 2023). "The mutagenesis of the ZKSCAN3 binding site reduced the luciferase activity of the Ct-SLCO1B3 reporter gene construct in the colorectal cancer cell lines DLD1 and T84 to 29.9% and 14.3%, respectively." (PMID 36986600, 2023). "Next, expression of the Ct-SLCO1B3 mRNA in the different colorectal carcinoma cell lines was analyzed by qRT-PCR." (PMID 36986600, 2023). "Our previous efforts concentrated on generating a potent RTM (RTM44) able to target Ct-SLCO1B3 and introduce the suicide gene HSVtk into colorectal cancer cells, rendering them sensitive to treatment with GCV." (PMID 35008999, 2022). "In the present study, we utilized RTM44, previously proven to target Ct-SLCO1B3 in a colorectal cancer model." (PMID 35008999, 2022). "Therefore, we cloned DNA fragments from the promoter regions of the Lt-SLCO1B3 and the Ct-SLCO1B3 gene and investigated their luciferase activity in hepatocellular and colorectal cancer cell lines." (PMID 36986600, 2023). "In line with the qRT-PCR analysis of Ct-SLCO1B3 mRNA expression, the luciferase activity of most reporter gene constructs was lower in Caco-2 cells compared to the luciferase activity in both other colorectal cancer cell lines." (PMID 36986600, 2023). "Furthermore, in all three colorectal carcinoma cell lines, the 100-Ct promoter fragment showed the highest luciferase activity, demonstrating that the core promoter of the Ct-SLCO1B3 gene is located within this DNA fragment." (PMID 36986600, 2023). "However, in all colorectal carcinoma cell lines, the Ct-SLCO1B3 promoter constructs showed a significantly higher luciferase activity in most of the comparisons." (PMID 36986600, 2023). "Besides the analysis of the different regulation of Lt- and Ct-SLCO1B3 gene expression, the focus of this work was the analysis of the Ct-SLCO1B3 promoter constructs in colorectal carcinoma cell lines." (PMID 36986600, 2023). "Thus, in two SLCO1B3-positive cell lines, such as colorectal carcinoma DLD-1 and bile duct carcinoma TFK-1 cells, CpG dinucleotides around the transcriptional start site were significantly hypomethylated." (PMID 36839686, 2023). "Notably, the efficacy of RTM44 has also previously been demonstrated in a colorectal cancer model, thereby highlighting its translatability to other malignancies that express Ct-SLCO1B3." (PMID 35008999, 2022). "The Solute Carrier Family 5 member 4 SLC5A4 Antisense RNA 1 (SLC5A4-AS1), Solute Carrier Organic Anion Transporter Family Member 1B3 (SLCO1B3), and ELFN1 Antisense RNA 1 (ELFN1-AS1) were identified as having an H3K4me3 peak in colorectal cancer cells but not in normal colon samples." (PMID 40141189, 2025).
Hyperbilirubinemia (14 papers, 2015 to 2026). An increased amount of bilirubin in the blood. "It is caused by pathogenic mutations in both SLCO1B1 and SLCO1B3 genes, and characterized by predominantly conjugated hyperbilirubinemia." (PMID 40901525, 2025). "In the dominant model, the SLCO1B3-rs2417940 CC genotype was related to a higher risk of hyperbilirubinemia (OR 3.138, p = 0.001)." (PMID 38279097, 2024). "In the additive model, alleles of the SLCO1B3-rs2417940 minor C (OR 2.889, p = 0.003) were associated with an increased risk of hyperbilirubinemia." (PMID 38279097, 2024). "Allele frequencies analysis revealed that the rs4148323 A allele in UGT1A1 gene and the allele C of SLCO1B3-rs2417940 were associated with hyperbilirubinemia (OR 2.897, p = 0.001 and OR 2.726,P = 0.001, respectively)." (PMID 38279097, 2024). "Our study demonstrated that the genotype CC and the frequency of allele C in the SLCO1B3-rs2417940 significantly correlated to the incidence of hyperbilirubinemia (81.3% vs. 58.0%, P = 0.002, OR 2.989 and 90.6% vs. 78.0%, P = 0.001, OR 2.726, respectively)." (PMID 38279097, 2024). "Common SLCO1B3 variants were found to be risk factors for hyperbilirubinemia in adults and neonates." (PMID 35754504, 2022). "Among the other 6 SNPs in the other 4 bilirubin metabolism genes, only rs2306283 in SLCO1B1 and rs2117032 in SLCO1B3 showed a suggestive association with neonatal hyperbilirubinemia risk." (PMID 26146841, 2015). "The frequencies of the A allele in UGT1A1-rs4148323 and the C allele in SLCO1B3-rs2417940 in the severe hyperbilirubinemia group (30.2% and 90.6%, respectively) were significantly higher than those in the controls (30.2% vs.13.0%, 90.6% vs. 78.0%, respectively, both p < 0.05)." (PMID 38279097, 2024). "In addition, the SLCO1B1 and SLCO1B3 polymorphisms also contributed to an increased risk of hyperbilirubinemia." (PMID 26146841, 2015). "Interestingly, simultaneous homozygous mutations in SLCO1B1 and SLCO1B3, resulting in disruption of hepatic reuptake of bilirubin, may account for the predominantly conjugated hyperbilirubinemia of Rotor syndrome." (PMID 31737051, 2019). "Our research indicated striking relationships between the vulnerability to severe hyperbilirubinemia and the gene polymorphisms for UGT1A1 and SLCO1B3." (PMID 38279097, 2024). "Rotor syndrome, a rare autosomal-recessive genetic disorder characterized by conjugated hyperbilirubinemia, is caused by biallelic pathogenic variants in both SLCO1B1 and SLCO1B3 genes." (PMID 32082363, 2019). "None of the haplotypes of SLCO1B1 and SLCO1B3 was found to be associated with hyperbilirubinemia." (PMID 38279097, 2024).
Rotor syndrome (12 papers, 2016 to 2025). Rotor syndrome (RT) is a benign, inherited liver disorder characterized by chronic, predominantly conjugated, nonhemolytic hyperbilirubinemia with normal liver histology. "This study provided evidence that the detected genetic mutations in SLCO1B1 and SLCO1B3 are common in Rotor syndrome, which is consistent with previous research." (PMID 40901525, 2025). "Here, for the first time, we report SLCO1B1 and SLCO1B3 gene mutations in Chinese patients with Rotor syndrome." (PMID 32082363, 2019). "Thus, precise identification of SLCO1B1 and SLCO1B3 pathogenic variants by genetic analysis should be used to confirm the diagnosis of Rotor syndrome and to provide guidance for therapeutic drug prescriptions and genetic counseling." (PMID 32082363, 2019). "Pathogenic SLCO1B1 and SLCO1B3 variants identified in patients with Rotor syndrome." (PMID 32082363, 2019). "At least one wild-type SLCO1B1 or SLCO1B3 allele prevents Rotor syndrome." (PMID 32082363, 2019). "In the current study, we examined SLCO1B1 and SLCO1B3 genes in two Chinese patients diagnosed with Rotor syndrome based on laboratory tests." (PMID 32082363, 2019). "Rotor syndrome is caused by homozygous or compound heterozygous pathogenic variants in both SLCO1B1 and SLCO1B3 genes." (PMID 32082363, 2019). "Here, we report two patients with Rotor syndrome in whom several pathogenic SLCO1B1 and SLCO1B3 variants were identified." (PMID 32082363, 2019). "The Rotor syndrome is caused by bi-allelic mutations in the SLCO1B1 and SLCO1B3 genes." (PMID 38651155, 2024). "Similar cases have been previously reported for Rotor syndrome, a LINE-1 insertion was shown to result in the skipping of exon 5 or exons 5–7 and the introduction of stop codons in SLCO1B3 transcripts from six Japanese patients." (PMID 32082363, 2019). "A study analyzing the genetic basis for Rotor syndrome, an autosomal recessive disorder, uncovered patients homozygous for a near full-length LINE-1 insertion (lacking 24 nt from the 5′-end relative to LINE-1.3) in intron 5 of solute carrier organic anion transporter family member 1B3 (SLCO1B3)." (PMID 27158268, 2016).
pancreatic cancer (10 papers, 2011 to 2023). "Several studies have found that SLCO1B3 is as well expressed in multifarious hormone-dependent cancers, such as prostate, testicular, and pancreatic cancer." (PMID 33397428, 2021).
cholestasis (8 papers, 2013 to 2024). Impairment of the bile flow caused by obstruction within the liver, or outside the liver in the bile duct system. "In the context of DILI, one of the proposed mechanisms of the cholestasis is the competitive inhibition of SLCO1B1 and SLCO1B3 transporters by RIF, thereby impairing hepatic uptake of bilirubin—their endogenous substrate." (PMID 38543282, 2024).
neutropenia (6 papers, 2017 to 2025). A decrease in the number of neutrophils found in the blood. "We now know that the genetic etiology of clozapine-associated neutropenia is complex and is likely to involve variants from several genes including HLA-DQB1, HLA-B and SLCO1B3/SLCO1B7." (PMID 30767710, 2019). "Together, the findings suggest the hypothesis that genetic variants at SLCO1B3 (and/or SLCO1B1) increase the risk of clozapine-associated neutropenia through a pharmacokinetic mechanism." (PMID 27400856, 2017).
lung carcinoma (5 papers, 2013 to 2023). "Interestingly, the overexpression of SLCO1B3 in non‐small cell lung cancer cells is known to regulate the epithelial‐mesenchymal transition (EMT) related genes." (PMID 37641095, 2023). "In 2012, Nagai and colleagues identified Ct-SLCO1B3 in human colon and lung cancer tissues." (PMID 34526411, 2021).
ovarian carcinoma (5 papers, 2013 to 2022). A malignant neoplasm originating from the surface ovarian epithelium. "A cancer-type variant with a distinct 5′region, termed cancer-type (ct)-SLCO1B3 coding for the cancer-type (ct)-OATP1B3 transporter was identified as the main OATP1B3 variant in colon, lung pancreatic, and also ovarian cancer." (PMID 30131693, 2018).
prostate tumors (5 papers, 2011 to 2023). "Prostate tumors expressed SLCO1B3 much more frequently than normal prostate tissues (62% vs. 0%, n = 21 and n = 5 respectively; P = 0.04) and more frequently with increasing Gleason score (P = 0.03)." (PMID 21625523, 2011).
chronic myeloid leukemia (4 papers, 2020 to 2024). "In chronic myeloid leukemia, a relevant decrease in imatinib clearance was associated with variant alleles of ABCB1 and SLCO1B3." (PMID 35456712, 2022).
endometrial cancer (4 papers, 2017 to 2024). Primary or metastatic malignant neoplasm involving the endometrium (mucous membrane that lines the endometrial cavity). "The deletion-only model identified a total of 59 gene loci associated (p < 0.01) with endometrial cancer, including two loci (SLCO1B3 and SALL3) that met the Bonferroni genome-wide threshold of significance." (PMID 39495297, 2024). "Several SLCO genes show altered expression in breast cancer, while in endometrial cancer only increased expression of SLCO1B3 was previously documented." (PMID 33917029, 2021). "The SLCO1A2, SLCO1B1, SLCO1B3, SLCO1C1, SLCO2B1, and SLCO4A1 genes were amplified in <1% of patients, but showed mutations (as mainly missense mutations), in 3.1–5.6% of 240 patients with endometrial cancer." (PMID 28674494, 2017).
liver disease (4 papers, 2021 to 2025). "SLCO1B1, SLCO1B3, and SLCO2B1 are highly expressed in the liver and play key roles in many liver diseases." (PMID 40734706, 2025). "SLCO1B1, SLCO1B3, and SLCO2B1 are highly expressed in the liver and play key roles in various liver diseases." (PMID 40734706, 2025).
cervical cancer (2 papers, 2010 to 2025). A primary or metastatic malignant neoplasm involving the cervix. "Our results strongly suggest the presence of a candidate gene signature comprising ATP1B3 and SLCO1B3 that holds predictive value for chemoradiotherapy response in cervical cancer." (PMID 40834150, 2025). "Our study suggests the presence of a candidate gene signature comprising ATP1B3 and SLCO1B3 that holds predictive value for cervical cancer." (PMID 40834150, 2025).
lymph node metastasis (2 papers, 2021). "The results showed that the expression of SLCO1B3 was associated with lymph node metastasis, histological grade, AJCC stage and Ki-67 (P < 0.05)." (PMID 33436824, 2021). "The study showed that high SLCO1B3 expression was associated with poor tumor differentiation, advanced disease stage, tumor invasion, lymph node metastasis, and poor OS." (PMID 34526411, 2021). "In this study, the results showed that SLCO1B3 high expression was significantly associated with the absence of lymph node metastasis, low histological grade and TNM stage." (PMID 33436824, 2021).
serous ovarian cancer (2 papers, 2017 to 2022). "In contrast, the SLCO1A2, SLCO1B1, SLCO1B3, SLCO1C1, SLCO2B1, and SLCO4A1 genes were amplified in 4.7–7.4% of a total of 316 patients with serous ovarian cancer, with concurrent amplification of SLCO1A2/1B1/1B3/1C1 and SLCO1B1/1B3/1C1, and also SLCO1B3/1C1." (PMID 28674494, 2017).
anemia (1 paper, 2025). A reduction in the number of red blood cells, the amount of hemoglobin, and/or the volume of packed red blood cells. "In addition, the borderline significant association of SLCO1B3 polymorphisms with anemia indicates a nuanced role in MTX-related hematological toxicity, thus requiring further investigation." (PMID 40732356, 2025). "Both SLCO1B3 polymorphisms (rs4149117, rs7311358) were significantly associated with anemia." (PMID 40732356, 2025).
asthma (1 paper, 2020). "The disease–gene association p-value scores (−1og10) in moderate asthma-related genes ranged from 3.2 (ZNF862) to 6 (PER2), while in severe asthma-related genes, it varied from 2.2 (TMCC1) to 6 (SLCO1B3, and WNK4)." (PMID 32512817, 2020).
breast tumors (1 paper, 2015). "Finally, as pCR is rarely achieved by NCT in ER+ breast tumors, we searched if BRCA1 (Pro871Leu), ERCC1 (Asn118Asn), CYP1B1 (Leu432Val) and SLCO1B3 (IVS12-5676) could stand for predictive markers of NCT for patients with this subtype of tumor." (PMID 26180747, 2015).
Cholestatic liver disease (1 paper, 2023). "Importantly, the solute carrier SLCO1B3 transports glycoursodeoxycholate, and this bile acid is used as a therapeutic agent to treat cholestatic liver disease." (PMID 36674967, 2023).
gallstones (1 paper, 2022). Solid crystalline precipitates in the biliary tract, usually formed in the gallbladder, resulting in the condition of cholelithiasis. "The aim of this study was to investigate the association between SLCO1B3 (rs4149117:G>T, rs7311358:A>G) and ABCC3 (rs4793665:T>C, rs11568591:G>A) genetic variants and susceptibility to cholesterol gallstone disease, as well as gallstone composition." (PMID 35328066, 2022). "We cannot exclude minor effects of SLCO1B3 and ABCC3 genetic polymorphisms on gallstone disease risk and gallstone composition, which could be masked by the variability of environmental factors within investigated patient populations." (PMID 35328066, 2022). "The results suggest that common polymorphisms in SLCO1B3 and ABCC3 genes are not a valuable marker of gallstone disease susceptibility and do not influence gallstone composition." (PMID 35328066, 2022). "The results of this study suggest that polymorphisms of SLCO1B3 and ABCC3 genes are not a valuable marker of gallstone disease susceptibility and do not influence gallstone composition." (PMID 35328066, 2022). "The components of gallstones were compared between the ABCC3 and SLCO1B3 genotypes." (PMID 35328066, 2022). "However, substantial variability in gallstone composition between individuals observed in the current study was not related to SLCO1B3 nor ABCC3 genotypes." (PMID 35328066, 2022).
hereditary hemochromatosis (1 paper, 2019). An inherited metabolic disorder characterized by iron accumulation in the tissues. "Unlike several other hereditary liver metabolic diseases, such as Wilson disease and hereditary hemochromatosis, the hotspots for SLCO1B1 and SLCO1B3 mutations are quite similar between different populations." (PMID 32082363, 2019).
Hypercholesterolemia (1 paper, 2022). An increased concentration of cholesterol in the blood. "The SLCO1B3 gene rs4149117 and rs7311358 polymorphisms have been shown to affect the efficacy of statin treatment in patients with hypercholesterolemia." (PMID 35328066, 2022).
ischemic stroke (1 paper, 2024). A stroke disorder caused by obstruction of blood flow to the brain, due to thrombotic (local blood clot formation) or embolic (due to a blood clot or other material traveling from another site) event. "The colocalization analysis did not reveal a shared causal variant between indirect bilirubin and the risk of ischemic stroke, based on the examination of 3 genes: UGT1A1, SLCO1B1, and SLCO1B3." (PMID 39210787, 2024).
Nausea (1 paper, 2021). A sensation of unease in the stomach together with an urge to vomit. "The objective for this study was to investigate whether MTX-induced nausea was associated with selected SNPs in candidate genes encoding MTX transporter proteins (SLCO1B1, SLCO1B3, SLC19A1, ABCB1, ABCC2), the MTHFR enzyme (MTHFR) and the 5-HT3-receptor (HTR3A, HTR3B), in children with JIA." (PMID 33794950, 2021).
retinoblastoma (1 paper, 2020). A malignant tumor that originates in the nuclear layer of the retina. "While DocR has been widely described, CabR remains fairly new with few single factors such as the Retinoblastoma tumor suppressor and the SLCO1B3 transporter which have been linked to Cab sensitivity." (PMID 32484838, 2020).
testicular cancer (1 paper, 2011). A primary or metastatic malignant neoplasm that affects the testis. "SLCO1B3 expression was also higher in testicular cancer (P = 0.02)." (PMID 21625523, 2011).
testicular tumors (1 paper, 2011). "In addition, SLCO1B3 expression was less frequent in testicular tumors (21% vs. 67%, n = 19 and n = 6 respectively; P = 0.06)." (PMID 21625523, 2011).
thrombotic thrombocytopenic purpura (1 paper, 2023). "SLCO2B1 and SLCO1B3 are involved in the steroidal hormone uptake, and thrombotic thrombocytopenic purpura (TTP) is linked with three SNPs present in SLCO2B1 expressed in various tissues." (PMID 37858151, 2023).